LEF1 (lymphoid enhancer binding factor 1)
Diseases named in the same sentence as LEF1 in open-access papers (continued):
Sharing a sentence is not in itself a finding about the gene and the disease.
lung adenocarcinoma (continued). "Additionally, we generated a LEF1/TCF4 as well as an AXIN2 signature, the latter as representative of WNT/β-catenin activity, following a bioinformatics approach with a gene expression dataset of cerebral metastases in lung adenocarcinoma." (PMID 23224985, 2013). "In conclusion, our data show that LEF1/TCF4, but not β-catenin, have prognostic relevance in primary and cerebrally metastasized human lung adenocarcinomas." (PMID 23224985, 2013). "Our data indicate that LEF1/TCF4, but not β-catenin, have prognostic relevance in primary and cerebrally metastasized human lung adenocarcinoma patients." (PMID 23224985, 2013).
acute myeloid leukemia (15 papers, 2013 to 2024). Acute myeloid leukemia (AML) is a group of neoplasms arising from precursor cells committed to the myeloid cell-line differentiation. "High expression of LEF1 has been identified as a favourable prognostic factor in cytogenetically normal acute myeloid leukaemia." (PMID 31703382, 2019). "Previous studies demonstrated that Sox4, RasGRP1, RasGRP3, IGF1R, CDK6, and LEF1 are the key oncogenes/tumor suppressor genes in acute myeloid leukemia." (PMID 31242922, 2019). "ALYREF was originally described as a transcriptional coactivator of the T-cell receptor α gene by binding LEF-1 and acute myeloid leukemia (AML)-1 transcription factors to form an enhancer-stimulating complex." (PMID 27679854, 2016). "Ectopic expression of LEF1 in HSCs induced acute myeloid leukemia-like or B cell ALL-like disease in mice, demonstrating LEF1’s oncogenic potential." (PMID 35514954, 2022). "This inhibitor suppressed the expression of WNT target genes (CCND1, LEF1 and TCF7) in mantle cell lymphoma (MCL) and strongly impaired cell proliferation and induced apoptosis in vitro in MCL and in acute myeloid leukemia (AML) cell lines." (PMID 34771683, 2021). "It was previously demonstrated that ordered expression of lymphoid enhancer-binding factor-1 (LEF-1) is necessary for normal hematopoietic stem cell function in mice, and that LEF-1 overexpression induces acute myeloid leukemia (AML)." (PMID 25805670, 2015). "Previous studies reported that lymphoid enhancer factor 1 (LEF1) expression and serum Galectin-3 level could affect clinical parameters and outcome in acute myeloid leukemia patients, but as far as we know, no study has addressed their combined effect on AML patients." (PMID 31929803, 2019). "High LEF1 expression is associated with favorable prognosis in acute promyelocytic leukemia (APL) and cytogenetically normal acute myeloid leukemia (AML), while it is a negative prognostic marker in adult B precursor acute lymphoblastic leukemia (B-ALL)." (PMID 26950276, 2016).
esophageal squamous cell carcinoma (15 papers, 2018 to 2025). Esophageal squamous cell carcinoma (ESCC) is a type of esophageal carcinoma (EC) that can affect any part of the esophagus, but is usually located in the upper or middle third. "LEF1 antisense RNA 1 (LEF1-AS1/LOC641518) is an antisense lncRNA encoded in the LEF1 locus, which is related to the metastasis in various tumors, including colorectal cancer and esophageal squamous cell carcinoma." (PMID 34256750, 2021). "Previously, it was reported that LEF1 drives stemness in esophageal squamous cell carcinoma by upregulating the TGF-β pathway and also facilitating EMT." (PMID 37509281, 2023). "MiR-34a-5p played an anti-esophageal squamous cell carcinoma (ESCC) role by targeting the Hippo-YAP1/TAZ signaling pathway while the expression of LEF1 was high in ESCC tissue and cell lines." (PMID 34299149, 2021). "For example, in our previous study, we found that miR‐34a‐5p could directly target LEF1 and promote epithelial–mesenchymal transition and progression in esophageal squamous cell carcinoma." (PMID 33463006, 2021). "Our previous study demonstrated that lymphoid enhancer-binding factor 1 (LEF1) could promote the progression of esophageal squamous cell carcinoma (ESCC)." (PMID 32760207, 2020). "Moreover, our previous study also reported that LEF1 was highly expressed in esophageal squamous cell carcinoma and was closely related to tumor progression and poor patient prognosis." (PMID 31296250, 2019). "In addition, overexpression of Lef1 promotes the tumorigenicity of Esophageal squamous cell carcinoma (ESCC) through the TGF-β signaling pathway." (PMID 36243826, 2022). "In line with previous findings in esophageal squamous cell carcinoma, these results confirm that lncRNA OXCT1-AS1 promotes NSCLC metastasis by stabilizing LEF1." (PMID 34337014, 2021). "In esophageal cancer, LEF1 activates the ERK/MAPK signaling pathway via the Id3/HRAS axis, thereby promoting the development and progression of esophageal squamous cell carcinoma (ESCC)." (PMID 40810004, 2025).
glioma (14 papers, 2013 to 2025). A benign or malignant brain and spinal cord tumor that arises from glial cells (astrocytes, oligodendrocytes, ependymal cells). "LEF1 promotes mesenchymal cell properties in EMT and was significantly associated with the overall survival of glioma patients." (PMID 40679044, 2025). "To gain insight into the impact of SUV39H2 on the underlying mechanism of glioma, we conducted luciferase reporter assays with hedgehog (GLI), Notch (RBP-JK), and Wnt (TCF/LEF1) luciferase reporters." (PMID 31636512, 2019). "It has been shown that miR-218 regulates glioma cell invasion by downregulating IkB kinase-b and LEF1." (PMID 29220380, 2017). "In the same way, HOXA13, belonging to the Homeobox (HOX) gene family, promotes glioma progression in part via Wnt- and TGF-β-induced EMT and, similar to LEF1, is a potential diagnostic biomarker for GBM and an independent prognostic factor in high-grade glioma." (PMID 29462960, 2018). "Moreover, we identified that several underexplored LARs, such as ESC O 2, HAT1(KAT1), and LEF1, may have prognostic value in lower grade glioma patients and may be potential glioma biomarkers." (PMID 33718432, 2021). "Subsequent multivariate Cox regression analysis indicated that three genes, EZH2, LEF1, and CASP1, exhibited significant prognostic value for glioma." (PMID 36389690, 2022). "The dysregulation of three necroptosis-related genes (EZH2, LEF1, and CASP1) was significantly related to the OS of glioma patients, especially those with older age, higher WHO grade, wildtype IDH status, and 1p19q codeletion status." (PMID 36389690, 2022). "In glioma stem cells, circRNA ARF1 is transcriptionally regulated by U2AF2 and circRNF121 in osteoarthritis is regulated by LEF1." (PMID 36072902, 2022). "We employed IHC to validate the protein expression of EZH2, LEF1, and CASP1 in 43 glioma tissues and matched paracancerous tissues." (PMID 36389690, 2022). "Among these LARs that showed increased expression with increasing WHO grade in both the CGGA and TCGA datasets, HDAC1 is the best-studied LAR in glioma, whereas the potential functions of ESCO2, KAT1, LEF1, and SLC16A10 are unreported in this cancer." (PMID 33718432, 2021). "Notably, WNT factors such as LEF1 and HOXA13 enhance cell migration and glioma development, particularly in high-grade gliomas 66,67." (PMID 40365286, 2025). "To conclude, our study revealed that the Pontin-LEF1 module plays a crucial role in driving TGFβR2 gene transcription, which could be exploited to target TGFβ/SMAD signalling for anti-glioma therapy." (PMID 36153326, 2022). "MiR-218 can directly target lymphoid enhancer-binding factor 1 (LEF1) and downregulate the expression of its downstream proteins, e.g., MMPs, reducing ECM degradation, whereas inhibition of miR-218 expression enhances glioma cell invasiveness, suggesting a tumor-suppressive role of the miRNA." (PMID 24202447, 2013).
gastric cancer (13 papers, 2014 to 2025). A primary or metastatic malignant neoplasm involving the stomach. "Here we report that the elevated expression of lymphoid enhancer binding factor 1 (Lef1) is associated with the TNM (tumor– node–metastasis) stage of gastric cancer." (PMID 32824603, 2020). "Conversely, selective inhibition of LEF1 induces apoptosis through the Wnt/β-catenin pathway, thereby suppressing gastric cancer cell growth." (PMID 40810004, 2025). "In gastric cancer, asporin, which is upregulated at various stages of gastric cancer, has been suggested to suppress the cancer cell apoptosis and promote cell proliferation by activating LEF1‐mediated gene transcription independently of β‐catenin." (PMID 39887653, 2025). "ESRRG has been identified as a candidate tumor suppressor gene in gastric cancer that can inhibit Wnt signaling via the suppression of transcription factor 4 (TCF4)/lymphoid enhancer-binding factor 1 (LEF1), binding to the Cyclin D1 (CCND1) promoter." (PMID 37240447, 2023). "Immunohistochemical results showed that the expression level of MMP7, CDH3, and LEF1 in gastric cancer tissues was higher than in the control group." (PMID 34485109, 2021). "Through the cubic spline interpolation algorithm, we found that the high-risk warning indicator of gastric cancer was 8<CDH3<15 and 10<expression of LEF1<16." (PMID 34485109, 2021). "A western blotting experiment was carried out, and the results showed that the relative expression levels of MMP7, CDH3, and LEF1 in gastric cancer tissues were increased compared with the control group." (PMID 34485109, 2021). "Our study has found that the elevated expression of LEF1—a key component of the Wnt-signaling pathway—correlates with the occurrence of gastric cancer." (PMID 32824603, 2020). "Our work identifies miR-183-96-182 cluster gene as a downstream target regulated by β-Catenin/TCF/LEF-1 pathway in gastric cancer cells." (PMID 24335145, 2014). "In this study, we found that miR-183-96-182 cluster inhibitors decrease the proliferation and migration of gastric cancer AGS cells and provide a functional link between GSK3β, the miRNA-183-96-182 cluster and the β-Catenin/TCF/LEF-1 pathway in gastric cancer." (PMID 24335145, 2014). "In summary, our findings identify a novel role for GSK3β in the regulation of miR-183-96-182 biogenesis through β-Catenin/TCF/LEF-1 pathway in gastric cancer cells." (PMID 24335145, 2014). "Here we report that inhibition of GSK3β increases nuclear translocation of β-Catenin, which forms a complex with TCF/LEF-1 to enhance miR-183-96-182 cluster gene expression in gastric cancer cells." (PMID 24335145, 2014). "This study shows that MMP7, CDH3, and LEF1 are highly expressed in gastric cancer tissues." (PMID 34485109, 2021). "The result demonstrated that MMP7, CDH3, and LEF1 might be identified as biomarkers for gastric cancer." (PMID 34485109, 2021). "The high-risk warning indicator of gastric cancer contained 8<CDH3<15 and 10<expression of LEF1<16." (PMID 34485109, 2021). "In our study, LEF1 was found to predict gastric cancer jointly with CDH3 and MMP7, which may be used as a diagnostic marker for gastric cancer in the future." (PMID 34485109, 2021). "This study showed that MMP7, CDH3, and LEF1 are highly expressed in gastric cancer tissues." (PMID 34485109, 2021). "Using miR array, ChIP assay, luciferase assay, qRT-PCR, we confirmed our hypothesis and identified miR-183-96-182 cluster as a novel target of the β-Catenin/TCF/LEF-1 pathway in gastric cancer cells." (PMID 24335145, 2014). "We hypothesized that GSK3β regulates miR-183-96-182 cluster through β-Catenin/TCF/LEF-1 pathway in gastric cancer cells." (PMID 24335145, 2014). "In gastric cancer, ASPN suppresses apoptosis in gastric cancer cells by regulating β-catenin-independent LEF1-mediated gene transcription." (PMID 40810004, 2025).
gastric cancer (continued). "Pearson’s correlation coefficient displayed that gastric cancer outcome was significantly correlated with the expression of MMP7, CDH3, and LEF1 (p<0.05)." (PMID 34485109, 2021). "Gastric cancer remained related to MMP7, CDH3, and LEF1 (p<0.05) in the univariate linear regression model." (PMID 34485109, 2021). "Meanwhile, asporin (ASPN) binds directly to LEF1, promotes LEF1-mediated gene transcription independent of β-catenin, and inhibits cell apoptosis in gastric cancer." (PMID 37553362, 2023). "CDH3, LEF1, and MMP7 can be used as candidate biomarkers to construct a neural network model from hub genes, which may be helpful for the early diagnosis of gastric cancer." (PMID 34485109, 2021). "Subsequently, 2,4-diamino-quinazoline (2,4-DAQ), a selective inhibitor of Lef1, was identified to suppress the expression of Wnt/β-catenin target genes such as AXIN2, MYC and LGR5 and result in the suppression of gastric cancer cell growth through the apoptotic pathway." (PMID 32824603, 2020). "Transcription factors MYB, MYBL2, ETV4, LEF1,TFAP2A were up-regulated in gastric cancer tissues." (PMID 25860484, 2015). "Specifically, five transcription factors MYB, MYBL2, ETV4, LEF1 and TFAP2A were up-regulated and they formed the TF-gene regulatory networks with 41 genes, 38 of which were up-regulated and 3 were down-regulated in gastric cancer tissues." (PMID 25860484, 2015). "Indeed, low PDZK1 correlated with LEF1 hyperactivity, whereas high PDZK1 did not, supporting the idea that PTEN C-tail hyperphosphorylation drives pro-tumorigenic WNT signaling in gastric cancers in which PDZK1 expression is compromised." (PMID 37225693, 2023).
glioblastoma (13 papers, 2016 to 2024). The most malignant astrocytic tumor (WHO grade IV). "Reducing LEF1 in glioblastoma multiforme cells restricts their ability to invade, migrate, and proliferate, as well as the self-renewal capability of stem-like cells." (PMID 39200196, 2024). "In the present study, we also observed a tendency of increased expression of a lymphoid enhancer-binding factor 1 (LEF1) in iPSC-derived glioblastoma and iPSCs-derived glioblastoma stem cells." (PMID 37509281, 2023). "The upregulation of miR-381 was also found to effectively inhibit EMT and metastasis by downregulating the transcription factor lymphoid enhancer-binding factor 1 (LEF-1) in glioblastoma." (PMID 35205289, 2022). "Several studies have shown the suppressive role of miR-381 (hsa-miR-381-3p) in cell metastasis and EMT in glioblastoma due to the suppression of LEF1 expression." (PMID 36354672, 2022). "LEF1 knockdown in glioblastoma multiforme cells inhibits invasion, migration, proliferation, and the self-renewal potential of stem-like cells." (PMID 34639214, 2021). "Low or lack of LEF1 expression was found in 61.1% of pilocytic astrocytomas, while 70% of glioblastomas showed strong LEF1 expression." (PMID 30468298, 2019). "The highest number of cells with strong LEF1 expression was in glioblastomas comparing to pilocytic (P < 0.001), diffuse (P = 0.032) and anaplastic types (P = 0.003)." (PMID 30468298, 2019). "Thus, pilocytic astrocytomas had significantly more cells with low LEF1 expression than both diffuse astrocytomas (P = 0.006) and glioblastomas (P = 0.001)." (PMID 30468298, 2019). "Similarly, the highest number of cells with strong LEF1 expression was confined to glioblastomas as compared with pilocytic (P < 0.001), diffuse (P = 0.032) and anaplastic types (P = 0.003)." (PMID 30468298, 2019). "This work demonstrates for the first time that FOXO1 promotes the expression of WNT pathway target genes LEF1 and TCF7 in basal‐like breast and glioblastoma multiforme cells." (PMID 37584250, 2023). "Knockout and suppression therapies designed for LEF1 have been shown to be effective in reducing tumor growth, migration, and invasion of CLL, CRC, glioblastoma multiforme (GBM), and renal cell carcinoma (RCC)." (PMID 34364397, 2021). "In addition, LEF1, β-catenin and Wnt3a as well as CD133 were found to be downregulated in iPSC-derived sFRP4 overexpressed glioblastoma cells compared to iPSC-GSCs." (PMID 37509281, 2023).
pancreatic cancer (13 papers, 2012 to 2025). "Recent attention has focused on the diagnostic value of CD99 and LEF1 in distinguishing SPNs from other pancreatic neoplasms." (PMID 40307756, 2025). "Upstream activators associated with WNT signaling in CF centroacinar cells included enhanced expression of LEF1 and TCF7L2 relative to WT centroacinar cells, which are known to be associated with enhanced proliferation in pancreatic cancer." (PMID 39687022, 2024). "Heatmap analysis in colorectal, stomach, and pancreas cancer patient datasets showed a consistent overlap between LBH overexpression and WNT signaling genes associated with pathway activation, i.e., WNT2, WNT5A, WNT11, LEF1, TCF4 or TCF7, CCTNB1, CCND1, JUN, DKK3." (PMID 37268816, 2023). "In addition, LEF1 expression in human pancreatic cancer correlates with advanced tumour stages." (PMID 22894607, 2012). "SPNs can be distinguished from other pancreatic tumors by the expression of CD10, paranuclear dot-like CD99 labeling and abnormal nuclear labeling for β-catenin or lymphoid enhancer-binding factor 1 (LEF1)." (PMID 27267993, 2016).
acute lymphoblastic leukemia (10 papers, 2015 to 2025). Leukemia with an acute onset, characterized by the presence of lymphoblasts in the bone marrow and the peripheral blood. "We explored the expression profile of LEF-1 in acute lymphoblastic leukemia (ALL) and determined its specific prognostic significance in this disease." (PMID 25805670, 2015).